INS (insulin)
Diseases named in the same sentence as INS in open-access papers (continued):
Sharing a sentence is not in itself a finding about the gene and the disease.
Insulin resistance (continued). "In rodent models of type II diabetes and insulin resistance, LXR agonists have been shown to reduce plasma glucose and improve glucose tolerance and insulin sensitivity." (PMID 26611207, 2016). "By this index, based on fasting glucose and insulin values, STAT was found to significantly increase insulin resistance in both males and females." (PMID 27124954, 2016). "In this study, we found that WPJ administration not only significantly decreased the serum levels of glucose and insulin but also decreased the HOMA-IR index, suggesting that WPJ improved high-fat diet-induced insulin resistance in mice." (PMID 26914024, 2016). "Homeostatic model assessment of insulin resistance (HOMA-IR) and area under the curve (AUC) for insulin, glucose, HOMA-IR and cortisol were calculated." (PMID 27191727, 2016). "Insulin resistance can be measured with an acute ITT, fifteen minutes after an insulin bolus (1 mU/g); skeletal muscle is harvested and immunoblots are used to determine the levels of phosphorylated pAkt at T308 and S473." (PMID 27547764, 2016). "Since moderate physical activity could improve the insulin resistance and further uptake of glucose in skeletal muscles, it is reasonable for subjects who are used to moderate physical activity possess lower fasting plasma glucose and better insulin sensitivity." (PMID 25993007, 2015). "The glucose tolerance and the insulin resistance were determined using an IPGTT and an IPITT, respectively, and the insulin decay rate was calculated from the insulin clearance." (PMID 25822220, 2015). "Researchers have found that CAV3-knockout mice develop insulin resistance in their skeletal muscles and that adenovirus-mediated gene transfer of CAV3 increases glycogen synthesis in the liver as well as improves insulin signaling in diabetic obese mice." (PMID 26674805, 2015). "The OGTT and ITT showed glucose intolerance and insulin insensitivity in SHR/cp rats, demonstrating their impaired glucose/lipid metabolism, hypertension and systemic insulin resistance." (PMID 25874615, 2015). "The concept of ‘selective insulin resistance’ is therefore critical for understanding the complex pathophysiology of T2DM, in which the insulin resistant state prevails in many tissues, but in a tissue-dependent, pathway-specific manner." (PMID 26615883, 2015). "To characterize insulin sensitivity of ZFDM rats at the prediabetic state, we performed ITT at 7 and 11 weeks of age. fa/fa rats at both ages exhibited severe insulin resistance." (PMID 25961052, 2015). "Therefore, insulin resistance may be induced by high insulin level." (PMID 26084330, 2015). "One developing theory of insulin resistance is that chronic oxidative stress activates kinases such as JNK and IKKβ, which inhibit activation of the insulin signaling intermediates." (PMID 25883987, 2015). "Homeostasis model assessment of insulin resistance (HOMA-IR) was calculated from fasting serum glucose and insulin." (PMID 26556598, 2015). "In contrast, maintaining a HFD of those insulin-treated diabetic mice overwhelms any potential benefit of EIT by promoting weight gain and worsening glucolipotoxicity and insulin resistance." (PMID 25633992, 2015). "Other limitations included the use of proxy measures of insulin resistance (HOMA-IR) and insulin secretion (HOMA-B)." (PMID 26154605, 2015). "In this study, we found that C. caudatus supplementation reduced serum fasting insulin level, improved insulin resistance indicated by a decreased HOMA-IR, and improved insulin sensitivity by an increased QUICKI." (PMID 26713097, 2015). "In the present study, the overweight group showed glucose, insulin, HOMA-IR, and hs-CRP than control group, indicating insulin resistance and increased inflammatory status than controls." (PMID 25781947, 2015).
Insulin resistance (continued). "Consequently, insulin was unable to act properly on resistant tissues and this resulted in poor glucose disposal and utilization; therefore, compensatory hyperinsulinemia due to enhanced β-cell secretion was an obligate accompanying feature in insulin resistance." (PMID 25838947, 2015). "Importantly, this constitutive UPR depends on insulin signalling, and disturbance of the INSR/P85/XBP1-mediated constitutive UPR in podocytes, for example, in type 1 diabetes (insulin deficiency) or type 2 diabetes (insulin resistance), is mechanistically linked with glomerular disease." (PMID 25754093, 2015). "Parameters related to insulin resistance and T2D including fasting plasma glucose (FPG), fasting plasma insulin (FPI) and hemoglobin A1c (HbA1c) were all significantly decreased indicating improved insulin sensitivity after weight loss." (PMID 26434764, 2015). "Common measures utilized by health professionals for the diagnosis of metabolic disease include HbA1c (%A1c), fasting glucose and insulin, estimated insulin resistance (HOMA-IR), estimated insulin sensitivity (Matsuda ISI) and/or an OGTT." (PMID 26030423, 2015). "This is in contrast with studies in other insulin-sensitive tissues that reported a link between TLR4 activation and insulin resistance through the upregulation of pro-inflammatory cytokines." (PMID 26539824, 2015). "They found that AGEs interact with insulin signaling pathways and interfere with glucose transport in KGN cells which can lead to development of insulin resistance and ovulatory dysfunction in conditions like PCOS." (PMID 26690206, 2015). "As previously reported, this group had a homeostasis model of insulin resistance (HOMA-IR) score of 2.7 ± 1.7 (standard deviation), placing them as a group in the insulin-resistant range." (PMID 26486974, 2015). "Moreover, systemic administration of FGF21 improves insulin sensitivity and relieves hyperinsulinemia in ob/ob, db/db mice, diet-induced obese mice and diabetic monkeys, which are consistent with our data that loss of FGF21 induces insulin resistance and hyperinsulinemia." (PMID 25811804, 2015). "In addition, the CaSR is expressed and functionally active in adipocytes, and may potentially regulate the peripheral actions of insulin, as highlighted by the finding of an association with the A986S CASR polymorphism and insulin resistance in patients with the polycystic ovarian syndrome." (PMID 25786244, 2015). "A recent study identified components of the insulin signaling pathway that are altered by HCV, conferring insulin resistance in the patient." (PMID 25691914, 2015). "These methods were Homeostasis Model Assessment Insulin Resistance (HOMA-IR), fasted plasma insulin (FPI), Quantitative Insulin Sensitivity Check Index (QUICKI), fasted glucose/insulin ratio (FGIR), HOMA2, and the McAuley index." (PMID 26273668, 2015). "PUFT was significantly and positively correlated with insulin and HOMAIR, suggesting that para- and perirenal fat accumulation is paralleled by a progressive increase in insulin resistance and insulin levels." (PMID 26419359, 2015). "Third, sex hormones during puberty such as oestrogen may influence insulin resistance; a rise in oestrogen level in females may enhance insulin sensitivity due to its role in suppressing secretion of glucagons and protecting against pancreatic insulin responses to glucose." (PMID 25970186, 2015). "The analyzed parameters: BMI, WHR, body composition (Tanita SC-330S analyzer), glucose and insulin levels in oral glucose tolerance test (OGTT), insulin resistance index (HOMA-IR), HbA1c, lipid profile, homocysteine, creatinine and creatinine clearance." (PMID 26512299, 2015). "The importance of the S1P2 receptor in insulin resistance was demonstrated by blocking the receptor using a specific antagonist (JTE-013), thereby increasing hepatic insulin signalling." (PMID 25866760, 2015).
Insulin resistance (continued). "Insulin resistance (HOMA-IR) was lower (0.79±0.041 vs 1.63±1.02, p<0.001) and insulin sensitivity (QUICKI) was higher (0.41±0.04 vs 0.36±0.03, p<0.001) in PWS." (PMID 26334732, 2015). "In this study, we demonstrated that HFD will induce insulin resistance (higher OGTT, leptin and F2-isoprostane, and lower adiponectin levels), partly through transcriptional modulation of insulin signaling genes." (PMID 26273674, 2015). "To gain insight into the protective mechanisms of Deepure tea against insulin resistance and hepatic steatosis in HFD-fed mice, we further examined the protein levels in hepatic tissue that are involved in insulin signaling and lipogenesis." (PMID 26504484, 2015). "However, in obese girls, we concluded that sodium intake could be the risk factor for obesity-induced insulin resistance, independent of BP, because BP and blood insulin, HOMA-IR, TG and LDL levels were not increased by high sodium intake." (PMID 25768006, 2015). "Insulin resistance as measured by HOMA was less (0.79±0.41 vs 1.63±1.02, p<0.001) and insulin sensitivity measured by QUICKI was increased (0.41±0.04 vs 0.36±0.03, p<0.001) in PWS compared to healthy controls." (PMID 26334732, 2015). "Those outcomes were homeostasis model assessment for insulin resistance (HOMA-IR) and Ferriman-Gallwey scale, fasting glucose, fasting insulin and glucose/insulin ratio, lipid profile and TNF-alpha, acne, infertility, and weight gain and testosterone level." (PMID 25653680, 2015). "SW with serum Mg concentrations <0.75 mmol/L showed differences in serum glucose, plasma insulin, QUICKI, HOMA-IR, and McAuley's index, indicating poorer glucose control and greater insulin resistance." (PMID 25947295, 2015). "Insulin resistance is usually evaluated by HOMA-IR, to a lesser degree by Matsuda index or ISI composite calculated by OGTT data and less by SI, an index of insulin sensitivity derived from IVGTT data calculated by minimal model analysis." (PMID 25944304, 2015). "Using two well-established models of fat-induced insulin resistance (acute lipid infusion and chronic HFD administration), we evaluated the effects of pharmacological TLR4 inhibition on peripheral and hepatic insulin action." (PMID 26196892, 2015). "In rodents and humans with obesity and insulin resistance, elevated expression and downstream signaling of TLR4 has been demonstrated in insulin-target tissues (muscle, liver and adipose tissue) and immune cells (monocytes and macrophages)." (PMID 26196892, 2015). "The deregulation of the brain insulin/IGF-1 signaling pathways influences energy metabolism and insulin resistance, and results in triggering pathological changes in the nervous and neuroendocrine systems." (PMID 28031898, 2015). "However, whether the observed reduced mitochondrial function in insulin-resistant human is causative or compensatory for the development of insulin resistance is not certain in experimental mice model." (PMID 26613076, 2015). "RBP4 as an adipokine has been shown to induce insulin resistance and GLUT4 to mediate insulin-stimulated glucose uptake in EF." (PMID 25935836, 2015). "Caution needs to be expressed in extrapolating the results of insulin resistance determined by the HOMA method reported here to measures of insulin resistance by other methods, such as insulin clamps or intravenous glucose tolerance tests." (PMID 26582398, 2015). "A commonly used estimate of insulin resistance is the homeostasis model assessment-insulin resistance index (HOMA-IR), which is proportional to the product of serum glucose and insulin levels in fasted animals." (PMID 26302954, 2015). "Associations between plasma levels of AGEs and fasting glucose, insulin and HOMA-IR as a measure of insulin resistance were weak (r between -0.2 and 0.2, all p>0.05)." (PMID 26018950, 2015).
Insulin resistance (continued). "The high prevalence of insulin resistance in PCOS also renders PCOS women 10 times more likely than controls to develop gestational diabetes and up to 5 times more likely to develop insulin-related complications such as spontaneous abortion." (PMID 26124830, 2015). "For example, PKCθ and -ε induce insulin resistance by inhibiting insulin receptor substrate 1 (IRS1) and the insulin pathway, while PKCδ and -λ have the opposite effect and stimulate the insulin pathway by activating IRS1." (PMID 26298773, 2015). "Nevertheless, we cannot exclude that insulin resistance could affect those organs at a later time since phosphorylation of IRβ is also significantly affected in skeletal muscle and there is an important trend towards reduced insulin-induced phosphorylation of IRβ in adipose tissue." (PMID 25757720, 2015). "A previous study using the glucose-insulin clamp technique reported lower insulin sensitivity in women with PCOS; in future, this would be the best way to characterize the degree of insulin resistance in women with PCOS." (PMID 26650926, 2015). "Insulin-treated diabetic mice but maintained on the HFD demonstrated even greater weight gain and insulin resistance compared to sham-treated mice." (PMID 25633992, 2015). "Among these Homeostasis model assessment of Insulin Resistance (HOMA-IR), Insulin sensitivity index (ISI) and Quantitative insulin sensitivity check index (QUICKI) have been extensively validated." (PMID 26219379, 2015). "Whether the elevated amino acids contribute to the development of insulin resistance, are a consequence of the defect in insulin action, or simply associated biomarkers, are not addressed by our study, but the magnitude of the associations renders these questions worthy of further study." (PMID 25952934, 2015). "In vivo insulin action was determined by conducting IAGT testing, a procedure that has been to detect diet-induced insulin resistance at more physiological relevant blood glucose levels than insulin tolerance testing." (PMID 26176546, 2015). "Insulin resistance in NAFLD is characterized by reduced whole-body, hepatic, and adipose tissue insulin sensitivity." (PMID 26569494, 2015). "Insulin seems to play a central role in the activation of SREBP-1c transcription, even with the presence of insulin resistance." (PMID 26630290, 2015). "Many reports have shown that reduced GLUT4 expression is related to insulin resistance, and improvement of GLUT4 content is related to increased insulin sensitivity." (PMID 25834641, 2015). "As LAP likely reflects insulin resistance, we aimed to investigate the accuracy of LAP in identifying OGTT abnormalities and to compare it to a widely used index of insulin sensitivity, the homeostasis model assessment of insulin resistance (HOMA-IR)." (PMID 25792981, 2015). "The higher levels of fasting insulin (increased by 21%) observed in n-STZ-treated animals are consistent with these results, corroborating that these rats developed insulin resistance." (PMID 26064993, 2015). "TNF-α or IL-6 downregulated insulin-stimulated glucose uptake and consumption in three types of cell lines, and casein injection decreased glucose and insulin tolerance in C57BL/6J mice, indicating that the inflammatory stress promoted insulin resistance." (PMID 26449763, 2015). "The treatment of mice with antagonists of melatonin receptors also led to insulin resistance, whereas the treatment with melatonin, on the contrary, increased the phosphorylation of AKT-kinase and restored insulin sensitivity." (PMID 28031898, 2015). "The homeostatic model assessment of insulin resistance (HOMA-IR) and Matsuda index were used to measure fasting and postprandial insulin sensitivity." (PMID 26500686, 2015). "Fasting glucose (4.9 ± 0.4 vs. 5.5 ± 0.5 mmol/L) and insulin (56.9 ± 38.9 vs. 61.8 ± 50.0 pmol/L) values were both unchanged, as was the HOMA measure of insulin resistance (1.8 ± 1.3 vs. 2.0 ± 1.5, all p > 0.05)." (PMID 26512691, 2015).
Insulin resistance (continued). "In the present study, IUGR increased insulin levels in the serum and HOMA-IR, which were used as markers of insulin resistance." (PMID 26317832, 2015). "Homeostasis model assessment of insulin resistance (HOMA-IR) was used to classify obese children/adolescents (n=72) as insulin resistant (n=37) and non-insulin resistant (n=35)." (PMID 25906397, 2015). "Comparing the two groups, higher fasting insulin levels and index HOMA values of insulin resistance were found in patients qualified for bariatric surgery." (PMID 26379783, 2015). "ZDF-SHAM rats had a significant increase in plasma insulin at POD14 and POD28 indicating a deterioration of insulin resistance." (PMID 25798945, 2015). "To confirm the effect of a HFD on insulin resistance, we measured blood glucose and serum insulin level, and performed glucose tolerance test (GTT) and insulin tolerance test (ITT)." (PMID 26518260, 2015). "However, one study of 8-year-old children compared the effect of milk and meat consumption on insulin resistance, and found a positive association between milk (but not meat) consumption and insulin concentration (103 %), insulin resistance (75 %), and C-reactive protein (26 %)." (PMID 26574072, 2015). "Homeostasis Model Assessment-Insulin Resistance (HOMA-IR) and QUICKI are the most widely used indices for assessing insulin sensitivity." (PMID 29546136, 2015). "As a consequence, IL-1β down-regulates the insulin-signaling in insulin target cells, providing a possible SFA-mediated inflammatory response resulting in insulin resistance." (PMID 26393565, 2015). "We therefore have used the duration of postoperative insulin infusion as a surrogate for recovery and found that, patients who had longer infusion durations had higher preoperative mean BMI, insulin levels, and HOMA-IR, suggestive of higher insulin resistance." (PMID 26322019, 2015). "Thus, LTB4 could promote insulin resistance by enhancing macrophage pro-inflammatory cytokine production, potentiating IL-1β action in insulin target organs and negatively affecting different components of insulin action." (PMID 26500652, 2015). "The levels of insulin and HOMA-IR were the same in HFD-OR and ND mice, whereas they were higher in HFD-OP mice, suggesting that HFD-OP mice possessed insulin resistance." (PMID 26592433, 2015). "Apart from decreasing insulin resistance, orlistat is reported to increase postprandial GLP-1 levels; thereby enhancing the insulin sensitivity and blunting the postprandial rise in blood glucose in type 2 diabetic patients." (PMID 26648813, 2015). "Obese subjects had higher fasting glucose and insulin concentrations, resulting in higher HOMA index, indicating insulin resistance." (PMID 26132294, 2015). "Fasting plasma insulin and TG concentrations and HOMA-IR, an index of insulin resistance, in OLETF rats fed PD were lower than in OLETF rats fed NC." (PMID 26606054, 2015). "Clearance of insulin is reduced with progressive CKD stage and insulin resistance appears at an earlier stage of CKD." (PMID 26635963, 2015). "Tcf7l2 overexpression in BAC/+ mice results in increased insulin secretion and glucose intolerance after high fat diet (HFD) due to peripheral insulin resistance." (PMID 25398947, 2015). "We assessed the homeostasis model assessment index for insulin resistance (HOMA-IR) and Gutt’s insulin sensitivity index (ISI)." (PMID 26277879, 2015). "HFD elicited insulin resistance and STZ administration reduced insulin levels, such that the animals were unable to maintain normal glucose levels and develop hyperglycemia." (PMID 26489513, 2015). "The vast majority of the studies in the literature assessed IR by the HOMA (Homeostasis Model Assessment of Insulin Resistance) and the QUICKI (Quantitative Insulin Sensitivity Check Index)." (PMID 26110878, 2015).